INS (insulin)
Diseases named in the same sentence as INS in open-access papers (continued):
Sharing a sentence is not in itself a finding about the gene and the disease.
diabetes (continued). "Endorsed by the Chinese Diabetes Injection Guidelines, these devices are gaining attention for their potential in insulin therapy." (PMID 41585790, 2025). "Diabetes mellitus (DM) is a chronic and progressive metabolic disorder resulting from inadequate insulin secretion or the body’s ineffective use of insulin." (PMID 40687577, 2025). "This review aims to enhance the understanding of insulin action, its biosynthesis and secretion, and pancreatic β-cell dysfunction contributing to diabetes." (PMID 40666490, 2025). "Secondly, as two classic peptides with proven uses, insulin and natriuretic peptides are of great significance and have broad innovation prospects for the treatment of diabetes and cardiovascular diseases." (PMID 40038239, 2025). "This underscores the importance of targeted educational interventions to enhance patient understanding of insulin pharmacology, reinforce safe handling practices, and promote holistic self‐care behaviors for optimal diabetes management." (PMID 41306599, 2025). "There is limited research looking specifically at insulin requirements or HbA1c in those with pre‐existing diabetes post‐transplantation." (PMID 40664615, 2025). "HCV eradication through antiviral therapy reduces hepatic complications and leads to improved metabolic outcomes, potentially reducing insulin resistance, enhancing beta‐cell function, and reducing the incidence of diabetes." (PMID 40539474, 2025). "IRS-2 KO animals show faulty hepatic insulin signaling and growth reduction in specific neurons and islet cells, which leads to diabetes when b cells are lost." (PMID 40141412, 2025). "The development of glucose-sensitive nanoparticle systems that mimic normal insulin pattern requirements has emerged as a significant advancement, bringing various potential solutions for better diabetes treatment." (PMID 40574088, 2025). "The relatively low proportion of insulin pump users in both groups (~10%) highlights an opportunity to expand access to advanced diabetes technologies." (PMID 41303901, 2025). "The beneficial effects of low-GI diets for decreasing postprandial blood glucose and insulin levels in the prevention and dietary management of diabetes have also been well-described." (PMID 40566351, 2025). "The design of this insulin continues to demonstrate scientific and clinical intent in improving diabetes mellitus management." (PMID 41155876, 2025). "Excessive production of inflammatory cytokines in diabetes is responsible for numerous harmful changes, such as impaired insulin signaling, insulin resistance, reduced intracellular glucose transport, β-cell failure, and damage to other cell kinds." (PMID 40806520, 2025). "Concurrently, she adjusted her lifestyle habits and compliance in terms of controlling her diabetes with semaglutide and insulin, with blood sugar ranging from 110 to 170 mg/dL (reference: <180 mg/dL for diabetics)." (PMID 41141029, 2025). "The results showed that patients with DR were younger, more likely to be female, had longer duration of diabetes, poorer glycaemic control, poorer blood pressure control, more insulin use, smaller AVR, and smaller PAVR compared to those without DR." (PMID 41343177, 2025). "This study has shown improved glycaemic control in patients with pre‐existing diabetes mellitus, illustrated by gradual reduction in insulin dose and oral anti‐glycaemic agent requirement in the months post‐transplant, with reduction in HbA1c." (PMID 40664615, 2025). "Type 2 diabetes mellitus (T2DM) is a multifactorial condition that includes insulin insensitivity and alterations in beta-cell dysfunction, causing severe vascular sequelae." (PMID 41030747, 2025). "After adjusting for diabetes status, only GCA and GDCA remained independently associated with insulin (p = 0.04 and p = 2.0e−3)." (PMID 40045464, 2025).
diabetes (continued). "Diabetes is a metabolic disorder characterized by chronic hyperglycemia resulting from inadequate insulin action, which is classified into several forms, including type 1 diabetes, type 2 diabetes (T2DM), gestational diabetes, and other rare types." (PMID 41471379, 2025). "Diabetes mellitus type 1 (insulin-dependent) (T1DM) is characterized by the selective destruction of the insulin-producing pancreatic beta." (PMID 39979315, 2025). "Studies have shown that the use of arginine can be used to mitigate diabetes as it induces insulin secretion." (PMID 40452790, 2025). "Diabetes is a condition characterized by chronically high blood sugar due to insufficient insulin secretion and/or the body’s resistance to insulin." (PMID 40104311, 2025). "Because of its modulation of adipocyte differentiation and sensitization of adipocyte to insulin, PPARγ agonists, such as rosiglitazone and other thiazolidinediones, have been employed for the treatment of diabetes." (PMID 41019996, 2025). "We provided the patient with education on diabetes management, including insulin injections and the use of a glucose sensor for continuous glucose monitoring." (PMID 41020242, 2025). "Noteworthy, a detailed study on flazine, identified in tomato juice, highlighted its potential in the treatment of diabetes by acting on insulin glycation/dimerization." (PMID 41295317, 2025). "We present the case of a 69-year-old woman with a medical history of diabetes mellitus, arterial hypertension, and knee osteoarthritis, for which she was receiving insulin, irbesartan, and hydrochlorothiazide." (PMID 40718305, 2025). "Mutant INS-gene-induced Diabetes of Youth (MIDY), a subtype of Maturity-Onset Diabetes of the Young (MODY), caused by insulin (INS) gene mutations is historically featured proinsulin misfolding." (PMID 40109403, 2025). "I had to ring my diabetes consultant and explain, and they had to ring the ward and said look, he knows what he's doing with his Insulin so please let him have his own pen." (PMID 39641494, 2025). "In diabetes, insulin is either low (type 1 diabetes) or hypofunctional due to resistance (type 2 diabetes) and glucagon secretion is higher in both cases, thus resulting in an increased glucagon/insulin ratio in terms of their biological action." (PMID 40305364, 2025). "Insulin resistance (IR), defined as the inability of insulin to increase the uptake of glucose by cells, is associated with obesity, type 2 diabetes mellitus (T2DM) and pre‐diabetes." (PMID 40033766, 2025). "In this study, we utilize high-throughput sequencing to uncover changes in m6A modification in diabetes mellitus by implementing intensive insulin therapy in people with diabetes." (PMID 40299682, 2025). "Estrogens, including estriol, are thought to protect against diabetes by enhancing insulin secretion and regulating glucose homeostasis." (PMID 40399988, 2025). "She had a history of diabetes, although the type was unclear at the time of presentation, for which she had previously been treated with insulin." (PMID 39786791, 2025). "Diabetes mellitus (DM) is a multifactorial disorder characterized by insulin resistance and insufficient insulin production, resulting in serious health complications." (PMID 40775689, 2025). "People with diabetes who use insulin (PWDI) face risks when they have a hospital admission and then return home." (PMID 40696540, 2025). "Diabetes was diagnosed at age 29 and was initially treated with oral hypoglycemics (metformin and sulfonylureas) but about 2.5 years later she was started on insulin due to insufficient glucose control." (PMID 40471292, 2025). "From a clinical perspective, insulin-sensitizing therapies have significant consequences for individuals with diabetes." (PMID 40280905, 2025). "The AX-enriched bread and the whole grain rye breads also led to higher insulin sensitivity, higher insulin responses, and delayed onset of diabetes compared to the control diet low in DF." (PMID 40362870, 2025).
diabetes (continued). "Triterpenoids in Poria cocos restore glucose homeostasis and enhance insulin sensitivity, crucial for diabetes management." (PMID 41552833, 2025). "From 2004 to 2010, influential keywords included “ischemia reperfusion injury,” “myocardial infarction,” “diabetes mellitus,” “oxidative stress,” “insulin resistance,” “heart failure,” “ROS,” “nitric oxide synthase,” and “infarct size”." (PMID 40441190, 2025). "Current diabetes management primarily emphasizes insulin or peptide derivatives, oral antidiabetic drugs, and dietary modifications." (PMID 40432897, 2025). "For example, TNF-α can interfere with the expression of genes related to insulin synthesis and secretion in beta cells, affecting the normal production of insulin, and thus, aggravating diabetes." (PMID 40650120, 2025). "Healthcare providers should ensure that patients and their families receive diabetes education, with a focus on insulin therapy, signs/symptoms, and management of hypoglycaemia and ketoacidosis." (PMID 40950999, 2025). "Technological advancements, like insulin pens, pumps, and portable glucometers, have transformed diabetes management." (PMID 40181799, 2025). "This principle has been applied to pancreatic cells to encourage available cells to sustain insulin levels in the body, thus serving as a secondary metabolite for treating diabetes." (PMID 40458480, 2025). "With respect to antidiabetic treatment, two patients with diagnosed diabetes mellitus were receiving insulin therapy, consisting of a combination of fast-acting and basal insulin." (PMID 39997354, 2025). "We used 2022–2023 electronic health record (EHR) data to identify adults with diabetes managed on insulin within a nurse practitioner–led diabetes program in primary care." (PMID 41246135, 2025). "To date, limited analysis has been conducted to understand how insulin bolus frequency and glucose monitoring frequency interact to support glycaemic management for people with diabetes on MDI therapy." (PMID 41039947, 2025). "Three studies reported on the effect of a hyperinsulinemic state on cancer survival using the following different indices: the dietary insulin index, empirical dietary index for hyperinsulinemia (EDIH), and diabetes risk reduction diet (DRRD)." (PMID 40005424, 2025). "These convergent mechanisms disrupt insulin secretion and glycemic homeostasis, driving diabetes pathogenesis." (PMID 41323015, 2025). "CircRNAs have served pivotally in diabetes‐related processes, including insulin synthesis, secretion, programmed apoptosis of pancreatic β cells, insulin resistance, and pancreatic inflammation." (PMID 39873909, 2025). "Induction of diabetes with streptozotocin and nicotinamide significantly reduced (p < 0.05) the serum insulin levels in the diabetic control group in comparison to the normal control group." (PMID 41227734, 2025). "While DBCM shares features with HFpEF, including diastolic dysfunction and preserved ejection fraction in early stages, it also arises from diabetes-specific mechanisms such as metabolic derangements, microvascular dysfunction and insulin resistance." (PMID 41153259, 2025). "In diabetes, persistent hyperglycemia and inflammation contribute to oxidative stress, leading to β-cell dysfunction and impaired insulin secretion." (PMID 40278284, 2025). "Diabetes mellitus is a chronic metabolic condition characterized by impaired insulin production or utilization, leading to dysregulation of blood glucose levels." (PMID 40765566, 2025). "Diabetes mellitus (DM) is a complicated and serious metabolic disorder characterized by abnormally high blood glucose levels that are due to impaired insulin secretion or action." (PMID 40429723, 2025). "This regulation influences the expression of related factors, resulting in beta cell apoptosis or necrosis, decreased insulin secretion, and increased insulin resistance, ultimately contributing to the onset or progression of diabetes." (PMID 40979172, 2025).
diabetes (continued). "Although insulin has been the most commonly issued treatment for diabetes, considerable effort has been directed toward developing alternative therapeutics." (PMID 40603733, 2025). "Both insulin secretion and resistance are essential events in the onset of diabetes, and mitochondrial dysfunction is also involved." (PMID 39835172, 2025). "GLP-1, widely used in diabetes treatment, enhances insulin secretion by promoting RyR-mediated CICR in beta cells." (PMID 40422193, 2025). "One month later, participants were able to independently perform at least one self-management activity (monitoring diabetes, preparing insulin, administering insulin, and rotating the infusion site)." (PMID 39852644, 2025). "One aspect of the DCCT intervention was frequent insulin dose adjustments by a diabetes care team member." (PMID 41283065, 2025). "Patients with prostate cancer and diabetes have lower PSA and testosterone levels and higher serum FBS, HbA1c, insulin, and IGF-1 levels, along with a deranged lipid profile, leading to observed greater cancer grade and high risk in men with diabetes." (PMID 41367482, 2025). "Perioperative management of diabetes prior to the onset of EuDKA was described in 12/30 (40%) cases, with most involving a regimen of pre or intra-operative insulin infusion with fluids and glucose (n = 8), whilst only fluids were commenced in four cases." (PMID 40887509, 2025). "The review included 17 articles and identified a total of 387 eyes treated with topical insulin for various ocular surface pathologies, with more than half of the patients (61%) having concomitant diabetes mellitus." (PMID 41303828, 2025). "The reduction in HbA1c found in our study also supports the recommendations of the SBD, which advises that individuals with diabetes mellitus using insulin should be instructed on dose administration on the basis of the amount of carbohydrates consumed." (PMID 41477679, 2025). "This increased incidence is primarily driven by COVID-19 infection and duration of diabetes (with insulin acting as a proxy)." (PMID 40804810, 2025). "C-peptide (CP), a peptide composed of 31 amino acids released by the pancreatic β-cells in the same equimolar ratio as insulin into the blood, is clinically used in monitoring pancreatic β-cell function and insulin needs in patients with diabetes." (PMID 40978759, 2025). "With diabetes treatment and increased insulin sensitivity, the hepatic glycogen content increases, and the insulin level declines to reach its average level." (PMID 40365188, 2025). "Diabetes mellitus (DM), a metabolic condition, is defined by elevated fasting blood glucose levels, insufficient insulin levels relative to body requirements, or insensitivity to insulin receptors." (PMID 40538685, 2025). "A large majority correctly identified diabetes as a condition of inadequate insulin production and recognised that excessive sugar intake can contribute to its development." (PMID 41555977, 2025). "Diabetes mellitus comprises a group of chronic metabolic diseases marked by persistent hyperglycemia arising from impaired insulin secretion, impaired insulin action, or both." (PMID 41375934, 2025). "Average diabetes duration was 11.5 ± 8.1 years, 38.8% used insulin, and average HbA1c was 8.6% ± 1.7." (PMID 39455481, 2025). "A total of 133 studies were found by searching for “Von Hippel-Lindau syndrome” combined with “diabetes,” “glucose,” or “insulin” in the past 10 years." (PMID 40989257, 2025). "Cinnamic acid demonstrated antidiabetic activity by enhancing glucose tolerance in rats with STZ-induced diabetes (5 and 10 mg/kg for 14 h) and inducing insulin secretion in isolated islets." (PMID 39861406, 2025). "Crocin and Conocarpus lancifolius extract exhibit significant therapeutic potential in the management of diabetes, offering multiple benefits including improved glycemic control, protection of vital organs, and modulation of insulin signaling pathways." (PMID 40569910, 2025).
diabetes (continued). "Hypoglycemia is the most frequent complication of insulin treatment in diabetes and is currently the major obstacle to achieving near normal glucose concentrations." (PMID 41510436, 2025). "Chronic hyperglycemia, which results from defects in insulin secretion, insulin action, or both, characterizes diabetes and often leads to severe complications." (PMID 40051514, 2025). "Insulin therapy is the cornerstone of diabetes treatment, with advancements such as insulin analogs and delivery pumps enhancing glycemic control." (PMID 40299682, 2025). "Based on the knowledge and expertise of medical professionals, the dataset includes several interpretable features such as BMI, insulin level, and the number of pregnancies, providing meaningful predictors for diabetes classification." (PMID 40627636, 2025). "After 1 yr, Eli Lilly introduced Iletin®, world's first commercially available insulin product for the treatment of diabetes; however, its drawbacks included short duration of action, multiple injections, high risk of hypoglycaemia, and allergic reactions." (PMID 40480914, 2025). "In June 2014, the second pulmonary insulin was launched in the United States (Afrezza®, Sanofi company) for patients with type 1 diabetes mellitus (T1DM)." (PMID 40703749, 2025). "With respect to diabetes-related variables, patients with multiple shots of insulin per day had higher disutility scores (parameter = 0.810, [0.256, 1.364], P = 0.00; reference: no or a single shot of insulin)." (PMID 40844966, 2025). "Intervention participants (n = 74 adults with insulin-requiring diabetes at FQHCs) self-enrolled and engaged with DSCs via text messages, phone calls, and events." (PMID 40678170, 2025). "This is particularly crucial as basal insulin contributes approximately 30% to 50% of total daily insulin use in individuals with type 1 diabetes mellitus (T1DM)." (PMID 41313183, 2025). "To address this limitation, we adjusted for several well-established proxies of obesity, including diabetes, hypertension, hyperlipidemia, insulin use, and CCI." (PMID 40427123, 2025). "In contrast, thiazolidinedione, an anti-diabetes drug used to increase insulin sensitivity, is known to have a more complex MoA and multiple targets." (PMID 40308216, 2025). "A higher prevalence of sarcopenia was reported in patients with diabetes, confirming that insulin dysfunction was related to sarcopenia." (PMID 39940262, 2025). "Our results suggest that high‐fibre diets improve fasting and postprandial glycaemia and reduce the likelihood of requiring insulin in women with diabetes in pregnancy." (PMID 39473074, 2025). "Diabetes mellitus (DM) is a metabolic disorder characterized by high blood glucose (hyperglycemia) due to defects in insulin production or action." (PMID 40648491, 2025). "Insulin-dependent diabetes mellitus (IDDM; type 1) is caused by impaired insulin production by the beta cells located in the islets of Langerhans of the pancreas." (PMID 41146794, 2025). "Diabetes, insulin, and hsCRP increased several-fold between the lowest and the highest BMI groups in both sexes." (PMID 40077610, 2025). "Metabolic dysfunction-associated fatty liver disease (MAFLD) and type 2 diabetes mellitus (T2DM) share overlapping pathophysiological mechanisms, including insulin resistance and chronic inflammation." (PMID 40943248, 2025). "Hypoglycemia, which is generally defined as a blood glucose concentration of <70 mg/dL (<3.9 mmol/L), typically occurs in patients with diabetes using glucose-lowering drugs or insulin." (PMID 41367919, 2025). "Morusin shows potential for managing diabetes by increasing insulin sensitivity through enhanced glucose uptake, and safeguarding pancreatic β-cells, thereby supporting insulin production." (PMID 41322309, 2025). "Diabetes mellitus has emerged as a critical global health challenge, characterized by chronic hyperglycemia resulting from defects in insulin secretion, insulin action, or both." (PMID 40173172, 2025).